CRY2 (cryptochrome circadian regulator 2)
Diseases named in the same sentence as CRY2 in open-access papers (continued):
Sharing a sentence is not in itself a finding about the gene and the disease.
anxiety disorder (1 paper, 2013). A category of psychiatric disorders which are characterized by anxious feelings or fear often accompanied by physical symptoms associated with anxiety. "Our objective was to study two core circadian clock genes, CRY1 and CRY2 as well as TTC1 that interacts with CRY2, in relation to depressive and anxiety disorders." (PMID 23951166, 2013). "The aim of the current paper is to study the associations of CRY1, CRY2 and TTC1 genes in depressive and anxiety disorders." (PMID 23951166, 2013).
Autoimmunity (1 paper, 2023). The occurrence of an immune reaction against the organism's own cells or tissues. "Thus, higher CRY2 expression in PHF21A_rs4756055*A carriers may improve resistance to autoimmunity." (PMID 38255677, 2023).
Azoospermia (1 paper, 2022). Absence of any measurable level of sperm,whereby spermatozoa cannot be observed even after centrifugation of the semen pellet. "Further bioinformatics mining revealed that related clock genes (PER1, PER2, CRY2, NR1D1 and NPAS2) were down-regulated in non-obstructive azoospermia patients." (PMID 35910569, 2022).
breast tumors (1 paper, 2018). "We found significantly decreased expression of CRY2, PER1, PER2 genes in the ER/PR negative breast tumors compared to the ER/PR positive tumors." (PMID 29958276, 2018).
celiac disease (1 paper, 2023). An autoimmune genetic disorder with an unknown pattern of inheritance that primarily affects the digestive tract. "CRY2 expression is also reduced in celiac disease, and Cry double knockout mice have an overactivated B cell receptor signaling pathway, contributing to high serum IgG concentrations and antinuclear antibodies, with severe lung and kidney involvement." (PMID 38255677, 2023).
cognitive decline (1 paper, 2024). "Overexpression of CRY2 led to decreased cognitive function in AD mice, and the downregulation of CRY2 attenuated the SD-induced cognitive decline in AD mice." (PMID 39012854, 2024). "The present study demonstrated that sleep deprivation (SD) led to cognitive decline in AD mice and increased the expression of CRY2 in the hippocampus." (PMID 39012854, 2024). "Inhibition or knockdown of CRY2 in the hippocampus attenuated the development of SD-induced cognitive decline in AD mice, and CRY2 overexpression promoted cognitive dysfunction in AD mice." (PMID 39012854, 2024). "The present study investigated the potential role of CRY2 in mediating sleep deprivation-induced cognitive decline in 5xFAD mice." (PMID 39012854, 2024). "The AD mice exhibited cognitive decline after 21 days of SD and had higher expression of CRY2 compared to AD mice with normal sleep." (PMID 39012854, 2024). "Our results suggest that the role of CRY2 in cognitive decline may be due to its interaction with CISH, which subsequently inhibits p-STAT1 expression." (PMID 39012854, 2024). "Overexpression of CRY2 in the hippocampal DG region of AD mice led to a decrease in cognitive function without SD, and knockdown of CRY2 protected against SD-induced cognitive decline in AD mice." (PMID 39012854, 2024).
Cognitive impairment (1 paper, 2021). Abnormal cognition is characterized by deficits in thinking, reasoning, or remembering. "Sleep-dependent memory was severely compromised in SCNCon mice, consistent with other reports of cognitive impairment in Cry1/Cry2-nulls." (PMID 34446572, 2021).
colitis (1 paper, 2022). Inflammation of the colon. "On the contrary, we found that in colorectal stromal cells, colitis was associated with decreases in the mRNA levels of Arntl, Clock, Cry1, Cry2, Per2, Per3, Nr1d1, Npas2, and BBR restored the expression of these genes except Per2." (PMID 36528592, 2022). "We also compared the expression of several key circadian genes including Arntl, Clock, Cry1, Cry2, Per1, Per2, Per3, Nr1d1, and Npas2 in colon samples collected at 03, 09, 15, and 21 of normal mice, colitis mice, normal mice receiving BBR, and colitis mice receiving BBR." (PMID 36528592, 2022).
colon adenocarcinoma (1 paper, 2021). "Compared to normal skin, patients with skin cutaneous melanoma (SKCM) present significant down-regulation in the expression of BMAL1, CRY1, CRY2, PER1, PER2, and PER3, and higher expression of CLOCK, a similar pattern was also observed in patients with colon adenocarcinoma (COAD)." (PMID 34966277, 2021).
colorectal tumour (1 paper, 2016). "High CRY2 and low FBXW7 expression in colorectal tumour tissue was correlated with chemoresistance as well as poorer survival of CRC patients." (PMID 26768731, 2016).
coronary artery disease (1 paper, 2025). "In aorta, we identified perturbations in a number of TFs involved in circadian clock regulation (CRY1, CRY2, PER2), vascular inflammation (PPARG, NR3C1), and those linked in coronary artery disease, including the estrogen receptor, ESR2." (PMID 39896461, 2025).
diffuse large B-cell lymphoma (1 paper, 2023). "The CC genotype of the CRY2 rs1401417 SNP was also associated with the risk of developing diffuse large B-cell lymphoma (DLBCL) and T-cell lymphoma, but no CRY2 SNPs were significantly associated with risk of developing marginal zone B-cell lymphoma (MZBL)." (PMID 37761843, 2023).
endometrial cancer (1 paper, 2018). Primary or metastatic malignant neoplasm involving the endometrium (mucous membrane that lines the endometrial cavity). "The polymorphism in CRY2 gene has been frequently found associated with increased risk or recurrence of breast and endometrial cancers." (PMID 29513728, 2018).
epilepsy (1 paper, 2015). A brain disorder characterized by episodes of abnormally increased neuronal discharge resulting in transient episodes of sensory or motor neurological dysfunction, or psychic dysfunction. "Finally, we showed that temporal differences of sampling can change experimental results for Per1, Per3, Bmal1, Cry1 and Cry2, but not for Clock, which was consistently decreased in rats with epilepsy in all comparison to the naive group." (PMID 26473354, 2015).
follicular thyroid carcinoma (1 paper, 2022). "Another study demonstrated alterations of clock genes, overexpression of BMAL1, and downregulation of CRY2, in patients with follicular thyroid carcinoma and PTC34." (PMID 36335214, 2022).
Hyperglycemia (1 paper, 2023). An increased concentration of glucose in the blood. "Humans with variants and polymorphisms of cryptochrome 2 (CRY2) and period circadian regulator 2 (PER2), which are key circadian rhythm genes, exhibit hyperglycemia." (PMID 37960204, 2023).
Immunodeficiency (1 paper, 2021). Failure of the immune system to protect the body adequately from infection, due to the absence or insufficiency of some component process or substance. "To validate in vivo the light‐induced cell killing mediated by LiPOP1, we generated a xenograft mouse model of solid tumors by injecting HeLa‐LiPOP1 cells or HeLa‐mCh‐CRY2 as the negative control into the flanks of immunodeficiency mice." (PMID 34540558, 2021).
in situ breast cancer (1 paper, 2025). "Cathepsin Z can mediate the effects of PRX, CRY2, ADCY3, and PELATON on in situ breast cancer." (PMID 39944834, 2025).
insomnia (1 paper, 2024). A sleep disorder characterized by difficulty in falling asleep and/or remaining asleep. "We observed that MTNR1B and CRY2 variants showed a robust temporal association in individuals who reported insomnia, late chronotype, or short sleep." (PMID 39091879, 2024). "We therefore tested if chronotype, sleep duration, insomnia, ease of awakening, daytime sleeping or daytime napping modulated the association between diurnal glucose and both the MTNR1B and CRY2 alleles." (PMID 39091879, 2024).
kidney cancer (1 paper, 2021). Primary or metastatic malignant neoplasm involving the kidney. "Five rhythmic genes, including PER2, DBP, PER3, CRY2, and RORA, have significant prognostic role in patient survival in at least two types of kidney cancer." (PMID 34977153, 2021).
kidney damage (1 paper, 2023). "Similarly, the pattern of reduction in the expression of metabolism-related genes was not sustained in the ClockΔ19 mice, thus suggesting that the deletion of Cry1 and Cry2 proteins is specifically associated with a metabolic derangement that can contribute to kidney damage." (PMID 37487638, 2023).
lung adenocarcinoma (1 paper, 2023). A carcinoma that arises from the lung and is characterized by the presence of malignant glandular epithelial cells. "Survival analysis further revealed that CRY1, CRY2, GPER1, and FBXL3 were negatively related to survival of lung adenocarcinoma patients, while TIM were positively related to survival." (PMID 37924048, 2023).
lymph node metastasis (1 paper, 2020). "The pooled ORs were 1.35 (95%CI: 0.84∼2.15, Ρ=0.214) forCry2 and differentiation, 0.85 (95%CI: 0.44∼1.66, Ρ=0.636) for Cry2 and invasion depth and 1.10 (95%CI: 0.80∼1.52, Ρ=0.543) for Cry2 and lymph node metastasis." (PMID 32437452, 2020).
malignant glioma (1 paper, 2022). A grade III or grade IV glioma arising from the central nervous system. "Since all three pathways act through AC020907.1, Y_RNA, TMEM72‐AS1, KRT16P2, DLX6‐AS1, AP002414.1, hsa‐miR‐424, TBPL1, NPAS2, and CRY2, these genes could serve as potential therapeutic targets for malignant glioma." (PMID 35194922, 2022). "The eleven genes within the circadian rhythm pathway (AC020907.1, Y_RNA, TMEM72‐AS1, KRT16P2, DLX6‐AS1, AP002414.1, hsa‐miR‐424, TBPL1, NPAS2, CRY2, and ETNK1) were used to construct a model to evaluate the importance of these genes in malignant glioma." (PMID 35194922, 2022). "During the process of illustrating the circadian rhythm pathway, among the 6 coding genes, we exhibited the biological functions of TBPL1, NPAS2, CRY2, and ETNK1; therefore, what are the roles of VPS33B and C9ORF40 in malignant glioma?" (PMID 35194922, 2022). "Fourteen genes within the cellular senescence pathway (AC020907.1, Y_RNA, TMEM72‐AS1, KRT16P2, DLX6‐AS1, AP002414.1, hsa‐miR‐424, TBPL1, NPAS2, CRY2, C9ORF40, AL136115.1, AC102941.1, and AC008738.2) were used to construct a model to evaluate the importance of these genes in malignant glioma." (PMID 35194922, 2022). "Fourteen genes within the tumour immune microenvironment pathway (AC020907.1, Y_RNA, TMEM72‐AS1, KRT16P2, DLX6‐AS1, AP002414.1, hsa‐miR‐424, TBPL1, NPAS2, CRY2, VPS33B, CT62, DPY19L2P1, and KCNH1‐IT1) were used to construct a model to evaluate the importance of these genes in malignant glioma." (PMID 35194922, 2022).
memory impairment (1 paper, 2013). "Memory impairments in Cry mutants are unlikely to result from low attention given that Cry1 and Cry2 mutant mice showed normal object exploration." (PMID 24187535, 2013).
paroxysmal AF (1 paper, 2021). "The expression of BMAL1, CRY2, NR1D2, PER2, and RORA was significantly lower in patients with persistent AF than in those with paroxysmal AF (persistent AF vs. paroxysmal AF, all p < 0.05)." (PMID 33430447, 2021).
placental abruption (1 paper, 2018). Vaginal bleeding preceding the 20th week of gestation. "Genetic variation in circadian rhythm genes ARNTL2, CRY2, DEC1, PER3 and RORA have also been associated with increased risk of placental abruption." (PMID 29768442, 2018).
renal carcinoma (1 paper, 2021). A carcinoma arising from the epithelium of the renal parenchyma or the renal pelvis. "However, the expression levels of PER1, PER2 in KIRC and CRY2 in KICH were significantly increased in tumor tissues, and they suggested subsequent in-depth investigation of the mechanisms underlying circadian abnormalities in these three renal carcinomas." (PMID 34977153, 2021).
Shock (1 paper, 2021). The state in which profound and widespread reduction of effective tissue perfusion leads first to reversible, and then if prolonged, to irreversible cellular injury. "Additionally, we found that NR1D1, NR1D2, CRY1, CRY2, PER1, PER2 and DBP had altered rhythms in at least some patients with septic shock." (PMID 33900485, 2021).
status epilepticus (1 paper, 2018). Status epilepticus is defined as a continuous seizure lasting more than 30 min, or two or more seizures without full recovery of consciousness between any of them. "In this study, we systematically evaluated the temporal expression of seven core circadian transcripts (Bmal1, Clock, Cry1, Cry2, Per1, Per2, and Per3) and the spontaneous locomotor activity (SLA) in post-status epilepticus (SE) model of mTLE." (PMID 30116220, 2018).
systemic lupus erythematosus (1 paper, 2025). An autoimmune multi-organ disease typically associated with vasculopathy and autoantibody production. "Mice deficient in cry1 and cry2 develop an autoimmune phenotype resembling features of human systemic lupus erythematosus (SLE)." (PMID 41415271, 2025).
thyroid (1 paper, 2021). "The expression levels of CLOCK, BMAL1 and PER2 in thyroid malignant group were significantly higher than benign and normal groups, while CRY2 was decreased, p < 0.05." (PMID 34211057, 2021). "We then chose CLOCK, BMAL1, CRY1, CRY2, PER1 and PER2 to observe the changes of circadian rhythm genes in thyroid malignant tissues." (PMID 34211057, 2021).
tongue cancer (1 paper, 2016). A malignant neoplasm affecting the tongue. "Of interest, the expression of key clock genes was either down-regulated, e.g., BMAL1, CLOCK, PER1, PER2, and PER3, or up-regulated, e.g. CYR1 and CRY2, in tongue cancer samples in relative to that in normal control samples." (PMID 27079271, 2016).
viral infection (1 paper, 2016). "This indicates that the IFI16 PY domain alone can increase the efficiency of CRY2 oligomerization, underscoring its function in assembly of IFI16 foci during viral infection." (PMID 27935834, 2016).
cancer (51 papers, 2010 to 2025). A tumor composed of atypical neoplastic, often pleomorphic cells that invade other tissues. "CRY2 also affects cancer risk and metabolism, with genetic variants associated with NHL affecting immune response and blood system development." (PMID 39566400, 2024). "There are no other publications where this genotype is associated with an increased cancer predisposition, but CRY2 rs10838524 was associated with winter depression among Finnish and Swedish populations." (PMID 31739444, 2019). "Although psychiatric disorders, cancer, and metabolic disorders are tightly connected with dysfunction of the biological clock, associations of CRY2 polymorphisms with morning/evening preference or other circadian phenotypes have not been described." (PMID 27529127, 2016). "We found that when kept in 24 hour alternating light-dark conditions (24hr LD cycles), mice deficient in Bmal1 (Bmal1+/−), Cry1 and Cry2 (Cry1−/−;Cry2−/−), Per1 and Per2 (Per1−/−;Per2m/m) or Per2 alone (Per2−/−) were all cancer-prone." (PMID 20539819, 2010). "The top intracellular pathways of the 12 overlapping genes were associated with circadian rhythms and entrainment (Arntl, Cry2, Per2, Per3, Bhlhe41), the cell cycle (Cdkn1a, Wee1), the oxytocin signaling pathway (Cdkn1a, Rcan1), and transcriptional misregulation in cancer (Cdkn1a, Per2)." (PMID 33668521, 2021). "However, the GT genotype of the CRY1 gene was the genetic variant with the lower risk of suffering cancer, as well as for those subjects carrying CC genotype of the CRY2 gene having an even lower risk." (PMID 30873119, 2019). "Likewise, lower CRY2 mRNA levels observed in CRC tissues strongly associated with cancer location, with the lowest levels detected in the transverse colon (p = 0.007)." (PMID 26768731, 2016). "As such, aberrant expression of CRY2 may influence carcinogenic processes and thereby impact cancer susceptibility." (PMID 20334671, 2010). "Furthermore, CRY1 and CRY2 isoforms have been differentially associated with cancer and may function as pro- or anti-tumorigenic factors depending on the type of cancer." (PMID 35153842, 2022). "Experimental study using primary mouse fibroblasts, genetic knockout mice (Cry2−/−), and human cancer cell lines to investigate CRY2 function." (PMID 41373479, 2025). "Mice with genetic disruptions of Per2, Bmal1, Cry1, and Cry2, which are regulatory factors of the circadian clock, spontaneously developed cancer in multiple organs, including the liver and ovaries." (PMID 37524704, 2023). "As TIMELESS expression was significantly upregulated and RORA, PER1, PER2, and CRY2 expression was significantly downregulated in most cancer types including LUAD and LUSC, it is necessary to probe their prognostic values." (PMID 35078435, 2022). "On the other hand, a previous reference indicated that CRY2 knockdown increased the phosphorylation of ERK 1/2 in cancer cells." (PMID 33902432, 2021). "Cry1 and Cry2 acted as transcriptional regulators and checkpoint proteins for cancer cell proliferation and cell cycle control." (PMID 32437452, 2020). "Clock genes are highly associated with activation or inhibition of oncogenic pathways, with CRY2 playing a dominant role in cancer development." (PMID 33042011, 2020). "proved that promoters of these clock genes (PER1, PER2, PER3, CRY1 and CRY2) were methylated in a variety of cancer cells, which resulted in their decreased expression." (PMID 27602964, 2016). "CRY2 has also been shown to be involved in cancer-relevant pathways including DNA damage checkpoint control and regulation of genes important for cell cycle progression." (PMID 20334671, 2010). "However, direct experimental evidence supporting these dual roles of CRY2 in cellular senescence and cancer progression is still limited." (PMID 40046513, 2025).